BANK1 (B cell scaffold protein with ankyrin repeats 1)
Diseases named in the same sentence as BANK1 in open-access papers (continued):
Sharing a sentence is not in itself a finding about the gene and the disease.
Autoimmunity (8 papers, 2013 to 2025). The occurrence of an immune reaction against the organism's own cells or tissues. "BANK1 has recently gained attention for its role in autoimmunity: BANK1-deficient mice show reduced levels of anti-dsDNA autoantibodies and decreased IL-6 production." (PMID 41516251, 2025). "The importance of the B cell scaffold with ankyrin repeats 1 (BANK1) in autoimmunity stems from a genome-wide association study that identified variants within this gene as inferring susceptibility for human SLE." (PMID 39163122, 2024). "We are providing a sensible explanation of the role of BANK1 in autoimmunity and support for BANK1 as a susceptibility gene for the disease." (PMID 27228057, 2016). "Bank1 has a major role in the development and transcriptomic pattern of both age-associated B cells and IFN-responsive B cells in autoimmunity." (PMID 39163122, 2024). "In short, the study of Bank1 is essential to understand its relationship with viral infections, autoimmunity, and the adequate treatment of disease." (PMID 39163122, 2024). "To date, the exact role of BANK1 in inflammatory diseases and autoimmunity remains incompletely understood." (PMID 39163122, 2024). "The B cell adaptor protein with ankyrin repeats (BANK1) and the B lymphoid tyrosine kinase (BLK) have been genetically associated with autoimmunity." (PMID 23555801, 2013). "In addition, a recent study with the relevant mice model of mercury-induced autoimmunity showed Bank1 and NF-κB as key regulators in anti-nucleolar antibody development." (PMID 36225928, 2022). "While ABCs appear to be cells of major importance in autoimmunity, we find that the ISG-expressing B cell population (CL3) is also importantly modulated by Bank1 and that Bank1 has an important role in determining the expression of ISGs." (PMID 39163122, 2024). "All these findings together suggest a role of Bank1 in the capability of ABCs to interact with Tefh cells, playing a crucial role in facilitating the ABC response and being activated during autoimmunity." (PMID 39163122, 2024). "It was recently shown that BANK1 shares, with other molecules, the presence of a conformational toll/IL-1 receptor domain (TIR), and this domain is coded by exon two; therefore, BANK1 could possibly play a role in toll-like receptor (TLR) signaling, important for autoimmunity." (PMID 30096841, 2018). "Because Bank1 is primarily expressed in B cells, our results imply that impairment of TLR7 signaling in B cells is not sufficient to trigger autoimmunity." (PMID 27228057, 2016).
primary Sjogren's syndrome (5 papers, 2013 to 2022). "With evidence for an association of BANK1 and RA, both BANK1 and BLK should be considered pleiotropic genes involved in the genetic background of distinct autoimmune phenotypes including SLE, SSc, Sjögren's syndrome and now RA." (PMID 23646104, 2013).
lymphoma (4 papers, 2017 to 2024). A malignant (clonal) proliferation of B- lymphocytes or T- lymphocytes which involves the lymph nodes, bone marrow and/or extranodal sites. "Lymphoma studies have indicated that Bank1 expression is predominantly found outside GCs, specifically in the mantle zone, where Bank1 exerts its influence in the extrafollicular areas." (PMID 39163122, 2024).
nephritis (4 papers, 2016 to 2023). Inflammation of renal tissue. "Accordingly, we also evaluated the potential association of CD40, BLK and BANK1 with the increased risk of nephritis or GI complications in our study." (PMID 36233442, 2022). "In the analysis of LN (n = 216) versus SLE without nephritis (n = 746), the strongest signal of association was identified for a SNP in BANK1 (p = 9.5 × 10−4)." (PMID 34127828, 2021). "A regional association plot of the BANK1 region based on the analysis of LN versus SLE without nephritis in the discovery cohort, revealed a cluster of highly linked SNPs in the first intron region." (PMID 34127828, 2021). "We found the association with BANK1 to be stronger in the analyses, LN versus controls and LN versus SLE without nephritis, than the SLE case-control and SLE without nephritis-control analyses, and conclude the association with BANK1 is mainly with LN." (PMID 34127828, 2021). "To further determine if the BANK1 association was primarily with LN and not SLE per se, we performed a post hoc case-control analysis of the discovery cohort comparing SLE, SLE without nephritis, and LN versus controls, respectively." (PMID 34127828, 2021).
B cell lymphoma (3 papers, 2020 to 2024). "The sole exception among these proteins is the B Cell Scaffold Protein with Ankyrin Repeats 1 (BANK1), which predominantly displays anti-tumoral functions in B cell lymphoma." (PMID 38335839, 2024). "Bibliographic search evidenced that MAL, BANK1, CXCR2, and KCNJ15 genes play a tumor suppressive role in different types of cancer, including colorectal cancer, B-cell lymphoma, and renal cell carcinoma." (PMID 32825087, 2020).
breast carcinoma (3 papers, 2014 to 2025). "The LIME results depicted BANK1 (cg00332153) as one of the top features for classifying primary breast cancer." (PMID 34359669, 2021). "We used receiver operator characteristic (ROC) analysis to compare the methylation status of BANK1 and CDKN1C in breast brain metastasis samples to a series of 48 early-stage primary breast cancer samples." (PMID 24489661, 2014).
diabetes (3 papers, 2021 to 2023). "We found multiple genomic variants in GSTCD, SKAP2, SLC9B1 and BANK1 genes to be present at a relatively higher frequency in our patient cohort indicating a causal connection between these variants and the incidence of type 1 diabetes mellitus in Qatar." (PMID 34556755, 2021).
Splenomegaly (3 papers, 2016 to 2025). Abnormal increased size of the spleen. "IMQ-treated WT mice that received P. distasonis presented a significantly reduced splenomegaly compared with IMQ-treated WT mice receiving PBS, but comparable to that observed in IMQ-treated Bank1-/- mice receiving PBS." (PMID 40761803, 2025).
COVID-19 (2 papers, 2021 to 2024). A disease caused by infection with severe acute respiratory syndrome coronavirus 2. "The second locus, with a PPH4 of 98.12% in critical COVID-19, was mapped to the BANK1 and SLC39A8 gene, also situated on chromosome 2." (PMID 38633255, 2024). "BANK1 also was found to be downregulated in the tears of COVID-19 patients." (PMID 34615949, 2021). "The most significant topSNP between COVID-19 and chronic pain was rs13135092, which mapped genes SLC39A8 and BANK1." (PMID 38633255, 2024).
leukemia (2 papers, 2021 to 2023). A malignant (clonal) hematologic disorder, involving hematopoietic stem cells and characterized by the presence of primitive or atypical myeloid or lymphoid cells in the bone marrow and the blood. "As for GZMB+ Bregs, we found that BANK1 was decreased in other subtypes of Bregs, including IL10+ and CD24hiCD38hi transitional regulatory B cells, along with BANK1 was down-regulated in activated/differentiated B cells, as in CD40-activated B cells, in leukemia and plasma cells." (PMID 33815360, 2021).
Arthritis (1 paper, 2018). Inflammation of a joint. "Based on the findings presented above, the present study was intended to evaluate BANK1 expression in peripheral B cells in the classic murine model of RA, the CIA mouse, its influence on changes in B cell phenotypes and correlation between BANK1 expression and the severity of arthritis." (PMID 29370826, 2018). "We first detected the effects of BANK1-regulated CIA-B cells (B cells from CIA mice with established arthritis) on CD4+ T cells isolated from DBA1/J mice in the presence of the specific CII antigen, which stimulates an antigen-specific reaction, to determine the function of these cells." (PMID 29370826, 2018). "In addition, the BANK1 mRNA level was negatively correlated with arthritis clinical scores and the levels of the three main anti-CII antibodies (anti-CII total IgG, IgG2a and IgG2b antibodies)." (PMID 29370826, 2018). "The BANK1 level decreased in the peripheral blood, spleen and lymph nodes of CIA mice, particularly during the acute stage of arthritis, and exhibited negative correlation with disease severity and autoantibody production." (PMID 29370826, 2018).
bipolar disorder (1 paper, 2024). A disorder of the brain that causes unusual shifts in mood, energy, activity levels and the ability to carry out day-to-day tasks. "Genes that were associated with brain volumes, depression, and schizophrenia or bipolar disorder includedAC011997.1,AKT3,BANK1,BOLL,DCC,HSPD1,HSPE1,HSPE1-MOB4,MOB4,PLCL1,RFTN2,SF3B1, andTRPS1." (PMID 40800518, 2024).
Cognitive impairment (1 paper, 2025). Abnormal cognition is characterized by deficits in thinking, reasoning, or remembering. "Among them, rs17199964 is a pleiotropic locus of BANK1 gene in 4q24 region, and bayesian colocalization analysis suggests that it is a causal locus shared between LHGS and cognitive impairment." (PMID 40893940, 2025).
follicular lymphoma (1 paper, 2013). Follicular lymphoma is a form of non-Hodgkin lymphoma characterized by a proliferation of B cells whose nodular structure of follicular architecture is preserved. "Next, we determined the kinetic of BANK1-PLCg2 PLA interaction in Daudi and follicular lymphoma derived RL B-cell lines upon IgM stimulation." (PMID 23555801, 2013).
gastric cancer (1 paper, 2025). A primary or metastatic malignant neoplasm involving the stomach. "The qPCR validation showed that PTPRC, SERPINB9, and RAC2 had low expression in gastric cancer cells, whereas only CCL20 and BANK1 were highly expressed." (PMID 40444282, 2025).
germinoma (1 paper, 2010). A malignant germ cell tumor arising in the central nervous system. "Six genes (BANK1, CXCL9, CXCL11, DDIT4L, ELOVL6 and HERC5) within 4q13.3-4q28.3 were more abundant in germinomas." (PMID 20178649, 2010).
inflammatory bowel disease (1 paper, 2024). A spectrum of small and large bowel inflammatory diseases of unknown etiology. "Additionally, STARD10 is linked to resilience against Paratuberculosis, STX2 against Escherichia coli, CCR9 shows potential for treating inflammatory bowel disease, and BANK1 regulates innate immune signaling in B cells." (PMID 38684985, 2024).
Large vessel vasculitis (1 paper, 2022). A type of vasculitis (inflammation of blood vessel walls) affecting large arteries such as the aorta and branches of the aorta. "It was also the case for the potential implication of BLK rs2736340 and BANK1 rs10516487 in Takayasu arteritis, another primary large-vessel vasculitis that involves mainly young individuals." (PMID 36233442, 2022).
Obesity (1 paper, 2018). Accumulation of substantial excess body fat. "Instead, our screen suggests that different nearby cis gene may be more fruitful for further functional follow up for obesity, namely ZCCHC8, VPS33A, RSRC2; SPDEF, NUDT3; SETD1, VKORC1; SGSM2, SRR; VASP, SIX5; OTX1; BANK1; ARIH1; ELL; CHST8, respectively." (PMID 29608557, 2018).
sleep disorder (1 paper, 2025). A change from the patient's baseline sleeping pattern, in the hours slept and/or an alteration/dysfunction in the stages of sleep. "Future studies should focus on the role of BANK1 in mood and sleep disorders, aiming to identify other than TLR7 and TLR9 upstream regulators involved in this pathway." (PMID 41516251, 2025).
tumor (10 papers, 2017 to 2025). "BANK1, which encodes a protein adaptor that is predominantly expressed in B cells, is a putative tumor suppressor gene in B-cell lymphomagenesis." (PMID 35910195, 2022). "We found that BANK1 was repressed in tumor B cells relative to normal B cells, consistent with the measured ATAC data." (PMID 37114830, 2023). "iCluster1 tumors also had specific changes in mRNA expression, including overexpression of BANK1, a crucial regulator acting as a tumor suppressor involved in both B-cell mediated humoral immunity and cellular immunity." (PMID 36418292, 2022). "This is concordant with the reduced level of BANK1 observed after B cell activation and in differentiated cells, as tumor B cells (GSE 22529) or plasma cells (GSE 6691), since Breg cells have also been shown to be highly differentiated cells and GZMB+ Bregs are enriched in plasmablast population." (PMID 33815360, 2021).
cancer (4 papers, 2017 to 2024). A tumor composed of atypical neoplastic, often pleomorphic cells that invade other tissues. "Differential expression and methylation of 3 selected candidates (BANK1, BIN2, and DTX1) were confirmed in an independent HNSCC cohorts from Johns Hopkins and TCGA (The Cancer Genome Atlas)." (PMID 28146432, 2017). "Finally, CNAtra successfully detected the previously-reported focal amplifications of MYC (NCI-H82) and MYCN (CHP-212, IMR-32) loci as well as homozygous focal deletions of BANK1/4q24 (NCI-H82), LKB1/STK11 (A427), and p16INK4a/CDKN2A (A427) loci in respective cancer cell lines." (PMID 32299346, 2020).
brain disease (1 paper, 2025). "A GWAS study suggests that BANK1 may be associated with brain disease susceptibility." (PMID 40893940, 2025).
skin disorder (1 paper, 2019). Any deviation from the normal structure or function of the skin or subcutaneous tissue that is manifested by a characteristic set of symptoms and signs. "Our study revealed very high frequencies (up to 95%) of chestnut horses harboring NFKB1, SLC39A8, BANK1 and UVSSA in ROH islands, and indicated evidence that these genes may be involved in the reported higher susceptibility of chestnut horses for skin disorders." (PMID 31261764, 2019).
BANK1 also shares sentences with these, for which no sentence is quoted: systemic sclerosis (5 papers); autoimmune thyroid disease (2); colorectal cancer (2); glomerulonephritis (2); interstitial lung disease (2); type I diabetes (2); atrial fibrillation (1); celiac disease (1); Chronic Lymphocytic Leukemia (1); cold urticaria (1); Crohn disease (1); depression (1); dermatomyositis (1); febrile seizures (1); generalized epilepsy (1); genetic diseases (1); giant cell arteritis (1); ischemia (1); lupus nephritis (1); polymyositis (1); psoriasis (1); renal cell carcinoma (1); sarcopenia (1); schizophrenia (1); Stroke (1); systemic vasculitis (1); Takayasu arteritis (1); type 2 diabetes mellitus (1); vasculitis (1); viral infections (1).